BAP1 (BRCA1 associated deubiquitinase 1)
Diseases named in the same sentence as BAP1 in open-access papers (continued):
Sharing a sentence is not in itself a finding about the gene and the disease.
conjunctival melanoma (6 papers, 2017 to 2025). "We reported the first cases of iris melanoma and conjunctival melanoma in association with BAP1-TPDS." (PMID 31382694, 2019). "The concurrence of conjunctival melanoma and BAP1-TPDS is remarkable in light of the low prevalence of both conditions." (PMID 31382694, 2019). "This is the first report where conjunctival melanoma has been identified in a patient with BAP1-TPDS." (PMID 31382694, 2019). "VP reduced proliferation in fast-growing UM cell lines with BAP1-positive or GNAQ/GNA11 mutations but was ineffective in BAP1-negative or conjunctival melanoma cell lines." (PMID 40177537, 2025). "Although most UM cell lines responded in vitro to VP, BAP1-negative and conjunctival melanoma cell lines did not." (PMID 33798262, 2021).
iris melanoma (6 papers, 2019 to 2025). A uveal melanoma that arises from the iris. "GNAQ, Guanine nucleotide-binding protein subunit alpha-11 (GNA11), EIF1AX, and BAP1 are commonly identified mutations in iris melanoma." (PMID 40491523, 2025). "Almost all UM in patients with a germline BAP1 mutation have tumors that are located posteriorly, although one iris melanoma has been described." (PMID 33396957, 2020). "Although the genetic basis of iris melanomas is still being studied, iris melanoma could be considered as a BAP1-TPDS-associated malignancy." (PMID 31382694, 2019). "Genetic analysis confirmed our previous observation that patients harboring a wildtype BAP1 gene or who had a UV-damaged iris melanoma lived longer, regardless of their GNAQ/GNA11 mutational status." (PMID 37377898, 2023). "Sequencing suggested that if the tumor was wildtype for BAP1 or a UV-damaged iris melanoma, then the patient was more likely to respond and have a more favorable survival." (PMID 37377898, 2023). "Low tumor burden, a wildtype BAP1 gene in the tumor or iris melanoma correlates with response and longer survival." (PMID 34453044, 2021). "Objective responses and/or prolonged survival were seen in patients with BAP1 wildtype tumors, and in one patient with an iris melanoma that exhibited a UV signature." (PMID 34453044, 2021). "Iris melanoma harbor GNAQ, GNA11 and EIF1AX mutations while BAP1 mutations and mutations in SF3B1 are less common or rare." (PMID 33396957, 2020). "Although UMs include iris melanomas, this is the first observation of an iris melanoma in a patient with BAP1-TPDS." (PMID 31382694, 2019). "Mutations in BAP1 are less frequently found in iris melanoma and not correlated with survival." (PMID 33396957, 2020).
Lynch syndrome (6 papers, 2020 to 2025). An autosomal dominant hereditary neoplastic syndrome characterized by the development of colorectal carcinoma and a high risk of developing endometrial carcinoma, gastric carcinoma, ovarian carcinoma, renal pelvis carcinoma, and small intestinal carcinoma. "Only 9 % had documented asbestos exposure, and genetic testing was limited to 5 patients (1 BAP1 mutation, 1 type 2 neurofibromatosis, 1 Lynch syndrome, 1 McCune-Albright and one negative)." (PMID 41409117, 2025).
neurofibromatosis (6 papers, 2019 to 2025). A hereditary neoplastic syndrome in which tumors grow in the nervous system. "The main risk factors for UM development include the presence of dysplastic nevus syndrome, choroidal nevi, ocular or oculodermal melanocytosis, familial syndromes including germline BRCA1-associated protein 1 (BAP1) mutations and neurofibromatosis." (PMID 33964953, 2021). "Most relevant predisposing factors for the development of UM are the presence of dysplastic nevus syndrome, choroidal nevi, ocular or oculodermal melanocytosis, familial syndromes including germline BAP1 (BRCA1-associated protein 1) mutations, and neurofibromatosis." (PMID 32992823, 2020).
thymoma (6 papers, 2022 to 2024). A neoplasm arising from the epithelial cells of the thymus. "Additionally, exclusive mutations in TCs were identified in BAP1 (14%), ABI1 (7%), BCL9L (7%), and CHEK2 (7%), while ZNF721 mutations (14%) and PABPC1 (14%) were uniquely associated with thymomas." (PMID 38338833, 2024). "Results for CD117, CD5, BAP1, MTAP, and TdT are similar to those previously published, as 32 out of 37 carcinomas and all thymomas in the present study were included in the prior study." (PMID 37190202, 2023). "In a recent study, nine out of thirty nine mutated genes (23%) were involved in epigenetic regulation, with 34% of TCs exhibiting recurrent mutations in seven of them (BAP1, ASXL1, SETD2, SMARCA4, DNMT3A, TET2, and WT1), an observation which was not present for thymomas." (PMID 38338833, 2024).
thyroid cancer (6 papers, 2022 to 2024). "Similarly, in thyroid cancer samples, the mRNA expression level of BAP1 was lower than that in normal samples, but its protein expression was higher." (PMID 39034372, 2024).
B cell lymphoma (5 papers, 2018 to 2025). "Consistently, BAP1 deficiency strongly reduced the constitutively overexpressed MHC-II genes in A20 murine B cell lymphoma cells without upregulating the bulk H2AK119Ub levels." (PMID 39817454, 2025). "Together, these results demonstrated that tumor-infiltrating immune cells were attenuated by loss of BAP1, promoting B cell lymphoma proliferation in vivo." (PMID 39817454, 2025). "Loss of BAP1 reduces immune cell infiltration and accelerates B cell lymphoma growth in vivo." (PMID 39817454, 2025). "Additionally, we demonstrated that pharmacological inhibition of polycomb repressive complex 1 (PRC1) — which deposits histone H2K119Ub and opposes BAP1 activity — can restore MHC-II gene expression in BAP1-deficient B cell lymphoma cells." (PMID 39817454, 2025). "Finally, to determine a potential combination effect of both PRC1 and PRC2 inhibitors on reactivation of MHC-II gene expression in BAP1-deficient B cell lymphoma cells, we treated BAP1-KO A20 cells with RB-3 or/and GSK126 for 6 days, followed by Western blot and FACS analysis." (PMID 39817454, 2025). "However, the loss of BAP1 leads to a substantial acceleration of B cell lymphoma cell growth in immunocompetent mice, indicating that BAP1 may function as a tumor suppressor via regulating TME and tumor immune response in this context." (PMID 39817454, 2025). "To further determine how loss of BAP1 accelerates B cell lymphoma cells growth in vivo via regulating immune cell infiltration and TME, we conducted single-cell RNA-Seq (scRNA-seq) with the tumor samples from both BAP1-WT and -KO tissues." (PMID 39817454, 2025). "Our study establishes the critical role of BAP1 as a transcriptional and epigenetic regulator in the GC reaction, which is a common site of cell transformation that gives rise to B cell lymphomas." (PMID 38529289, 2024). "For instance, BAP1 was previously shown to facilitate DNA repair through the homologous recombination (HR) pathway in DT40 B cell lymphoma." (PMID 38529289, 2024). "In contrast, the growth of a T cell leukemia cell line (Jurkat) and a B cell lymphoma cell line (Raji) were unaffected by BAP1 depletion." (PMID 30013160, 2018). "Besides the human cancer cell lines, we also knocked out BAP1 in a mouse B cell lymphoma cell line A20, which constitutively overexpresses MHC-II cluster genes." (PMID 39817454, 2025). "In our current studies, we demonstrated that inhibition of PRC1 activity by its specific small molecule inhibitor RB-3 could at least partially rescue the transcriptional defect induced by BAP1 depletion in B cell lymphoma cells." (PMID 39817454, 2025). "However, to date, the role of BAP1 in regulating B cell lymphoma development remains to be elucidated." (PMID 39817454, 2025). "Interestingly, in our current studies, we found that BAP1 controls different transcriptional programs in B cell lymphoma other than in normal B cells." (PMID 39817454, 2025). "Although B cell lymphomas are not commonly associated with BAP1 mutations, cases of non-Hodgkin lymphoma have been reported in carriers of germline BAP1 mutations." (PMID 33912157, 2021). "Therefore, we anticipate that future work in the Bap1fl/fl Cγ1-cre and other relevant murine models may further explore BAP1 functions as a tumor suppressor in B cell lymphoma." (PMID 38529289, 2024). "In summary, our studies have uncovered a potential role of histone H2AK119 deubiquitinase BAP1 and the epigenetic balance between PRC1 and BAP1 in regulating MHC-II gene expression and TME in B cell lymphoma cells." (PMID 39817454, 2025). "Moreover, BAP1 has not been previously found to be mutated in B-cell lymphomas." (PMID 33180881, 2020). "In our current studies, we demonstrated that PRC1 is responsible for the transcriptional repression of MHC-II genes upon BAP1 depletion, as inhibition of PRC1 could largely rescue the gene-expression defect in BAP1-depleted B cell lymphoma cells." (PMID 39817454, 2025).
B cell lymphoma (continued). "To further explore the roles and mechanisms of BAP1 activity in B cells, we targeted Bap1 gene using CRISPR/Cas9 in the CH12F3 B cell lymphoma line, which is a commonly used model for the analyses of B cell activation, class switching, and associated cellular processes." (PMID 38529289, 2024). "Notably, the depletion of BAP1 does not affect cell-cycle or proliferation genes and has a mild effect on B cell lymphoma cell viability in vitro." (PMID 39817454, 2025). "Moreover, to validate whether the BAP1/IRF1/CIITA axis is a major regulator of MHC-II genes’ expression in B cell lymphoma, we restored IRF1 in BAP1-KO A20 cell followed by RNA-Seq analysis and FACS analysis." (PMID 39817454, 2025).
cervical cancer (5 papers, 2017 to 2025). A primary or metastatic malignant neoplasm involving the cervix. "The aim of this study was to validate the potential role of miR-31 and BRCA1-associated protein-1 (BAP1) on regulating epithelial-mesenchymal transition (EMT) in cervical cancer." (PMID 29159179, 2017). "One study on cervical cancer cell lines reported that BAP1 knockdown induced increases in N-cadherin and vimentin and a decrease in E-cadherin (which are hallmarks of EMT) and increased cell migration." (PMID 37240204, 2023). "Our study showed that miR-31 induced EMT via regulating BAP1 expression in cervical cancer cells and marked the expression of E-cadherin downregulated and N-cadherin and vimentin upregulated." (PMID 29159179, 2017). "Taken together, these data indicate that BAP1 is a key effector of invasion and migration in cervical cancer, which was regulated by miR-31." (PMID 29159179, 2017). "To further investigate the correlation between miR-31 and BAP1, we use qRT-PCR assay to detect the level of miR-31 and BAP1 expression in cervical cancer tissues and adjacent normal tissues." (PMID 29159179, 2017). "In this study, we showed that BAP1 was a direct target of miR-31 and an inverse correlation between miR-31 and BAP1 expression in cervical cancer cells and tissues." (PMID 29159179, 2017). "In summary, we demonstrated that miR-31 can induce EMT by downregulating BAP1 in cervical cancer, and miR-31-induced acceleration of cellar migration and invasion was partially by its regulation of BAP1 in vitro and in vivo." (PMID 29159179, 2017). "However, miR-31-5p is expressed at increased levels in human cervical cancer cells and clinical tissues, and accelerates tumor growth and development in vivo by inhibiting the expression of BAP1." (PMID 41002382, 2025). "In general, miR-31 interference with BAP1 recovery expression may be a potential therapeutic strategy for metastatic cervical cancer patients." (PMID 29159179, 2017). "Overall, these results highlight an important role of miR-31 functioning as an oncomir which could promote EMT in cervical cancer via downregulating BAP1 expression." (PMID 29159179, 2017). "The results above suggest that BAP1 overexpression reverses the effect of miR-31 on tumor growth and miR-31 could promote tumor growth by silencing BAP1 expression in cervical cancer." (PMID 29159179, 2017). "We further examined whether BAP1 was a direct target of miR-31 in cervical cancer cells using dual-luciferase reporter assay." (PMID 29159179, 2017). "Furthermore, the results revealed that miR-31 promoted proliferation and EMT in cervical cancer cells and accelerated the development of tumor growth in vivo xenograft experiment by inhibiting BAP1 expression." (PMID 29159179, 2017). "BAP1 may function as a tumor suppressor in cervical cancer; it is very significant to inhibit miR-31 to induce BAP1 expression." (PMID 29159179, 2017). "BAP1 was a direct target of miR-31; downregulation of BAP1 by miR-31-induced EMT in cervical cancer." (PMID 29159179, 2017). "However, there has very little research on the role of BAP1 in cervical cancer and the relationship between miR-31-BAP1 and EMT has not yet been reported." (PMID 29159179, 2017).
hereditary cancer (5 papers, 2020 to 2024). Malignant neoplasms occurring in families at a rate greater than that expected by chance and caused by germline mutations in a specific gene. "It seems that BAP1 germline mutations cause a predisposition to hereditary cancers which may be more aggressive and emerge earlier in life." (PMID 34771510, 2021). "BRCA1-associated protein 1 (BAP1) is a tumor suppressor and deubiquitinase whose mutations increase the risk of several types of familial cancers." (PMID 35052618, 2022).
liver cancer (5 papers, 2017 to 2025). An epithelial or non-epithelial malignant neoplasm that arises from the liver. "To clarify this association, we evaluated the effects of BAP1 suppression on the expression of stemness genes in liver cancer cells." (PMID 29018224, 2017).
myelodysplastic syndrome (5 papers, 2013 to 2021). A clonal hematopoietic disorder characterized by dysplasia and ineffective hematopoiesis in one or more of the hematopoietic cell lines. "Another recent study found that BAP1 loss leads to a myelodysplastic syndrome (MDS) in mouse." (PMID 23915344, 2013). "Intriguingly, while germline loss of Bap1 in the mouse results in embryonic lethality, somatic loss has been associated with the development of a myelodysplastic syndrome, a disease not normally associated with loss of BAP1 in humans." (PMID 28062663, 2017).
neuroblastoma (5 papers, 2018 to 2023). Neuroblastoma (NB) is the most common solid, extracranial childhood tumor. "A novel mechanism for BAP1 has been proposed in neuroblastoma demonstrating that the association between BAP1 and 14-3-3 protein can induce the release of the apoptotic inducer protein Bax from 14-3-3 and so promoting cell death through the intrinsic apoptotic pathway." (PMID 31766522, 2019). "To analyze, whether 14-3-3 can undergo ubiquitination, the overall levels of ubiquitin-associated 14-3-3 in BAP1- or empty plasmid-transfected neuroblastoma was investigated." (PMID 29686263, 2018). "For example, BAP1-induced apoptosis in neuroblastoma cells is mediated via an interaction with the 14-3-3 protein; thus, the loss of the 14-3-3 protein may lead to loss of BAP1 function (at least partially), even when BAP1 mRNA and DNA are normally expressed." (PMID 32028647, 2020). "Here, we characterized a molecular mechanism and translational significance of BAP1-mediated deubiquitination of MYCN in neuroblastoma." (PMID 37543638, 2023). "The comparison of growth rate between neuroblastoma cells revealed that low-expressing BAP1 cells, SK-N-DZ cells showed an elevated proliferation rate and cell cycle progression, as well as reduced cell death compared with BAP1 expressing SK-N-F1 cells." (PMID 29686263, 2018). "Two different strategies were applied to analyze the mechanism of BAP1 inducing cell death in neuroblastoma." (PMID 29686263, 2018). "In summary, our present findings suggest that the reduced expression of BAP1 triggers neuroblastoma cells to survive and grow faster compared to the BAP1 expressing cells." (PMID 29686263, 2018). "The restoration of BAP1 expression in neuroblastoma cells facilitated cell death mediated by direct interaction with 14-3-3 and releasing Bax from this complex." (PMID 29686263, 2018). "It was found that the pro-apoptotic function of BAP1 is mediated via binding to 14-3-3 protein, which further facilitated cell death signaling in neuroblastoma." (PMID 29686263, 2018). "In this study, we found that BAP1 was downregulated both at the RNA and protein level in a subset of neuroblastoma cell lines." (PMID 29686263, 2018). "In cell cycle synchronized neuroblastoma cells, we monitored the commitment of BAP1 expressing cells to apoptosis after release." (PMID 29686263, 2018). "To investigate the role of BAP1, we overexpressed full-length BAP1 or BAP1-C91A in different neuroblastoma cell lines." (PMID 29686263, 2018). "It was evident that the weight and mass of BAP1 stably expressing tumors were markedly reduced compared to control mice, confirming the effects of BAP1 on neuroblastoma cell growth in vivo." (PMID 29686263, 2018). "In summary, our study uncovers a new mechanism for BAP1 in the regulation of cell apoptosis in neuroblastoma cells." (PMID 29686263, 2018). "In this study, we found that the reduced expression of BAP1 pro6motes the survival of neuroblastoma cells, and restoring the levels of BAP1 in these cells facilitated a delay in S and G2/M phase of the cell cycle, as well as cell apoptosis." (PMID 29686263, 2018). "In this study, we investigated the role of BAP1 as a tumor suppressor gene in neuroblastoma based on the 3p-chromosomal location of BAP1 and that alteration in chromosome arms 3p is a common event in neuroblastoma." (PMID 29686263, 2018). "Our findings further indicate that BAP1 could be a potential therapeutic target for MYCN-amplified neuroblastoma." (PMID 37543638, 2023). "Importantly, the physiological role of BAP1 in neuroblastoma remains largely unexamined which urges us to examine the roles of BAP1 in NB." (PMID 37543638, 2023). "Furthermore, transient transfection of neuroblastoma with increasing concentrations of the BAP1-cDNA showed a direct correlation between levels of BAP1 expression and cell death." (PMID 29686263, 2018).
neuroblastoma (continued). "In order to investigate whether BAP1 expression is altered in neuroblastoma, we studied the levels of BAP1 expression in different neuroblastoma cell lines." (PMID 29686263, 2018). "Therefore, targeting BAP1 by its inhibitors such as iBAP-II or in combination with other therapeutic strategies might be an effective treatment strategy for human neuroblastomas with amplified MYCN which warrants further in deep investigation." (PMID 37543638, 2023). "Monitoring cell morphology of neuroblastoma cells expressing full-length BAP1 showed that these cells but not the cells expressing a control plasmid or the cells expressing a catalytically inactive mutant of BAP1 (BAP1-C91A) facilitated neurite outgrowth 72–96 h post transfection." (PMID 29686263, 2018). "The interaction between BAP1 and 14-3-3 protein was confirmed by performing the co-IP of FLAG-tagged BAP1 and pull-down of endogenous 14-3-3 in neuroblastoma cells." (PMID 29686263, 2018). "The analysis of gene expression array data of 102 neuroblastomas (Stage 4 and non-MYCN amplified) showed that there is a trend toward the association between high BAP1 and Bax expression and better relapse-free survival of the patients." (PMID 29686263, 2018). "Testing the total levels of 14-3-3 in the neuroblastoma cells, we found no changes in the cell lines harboring reduced levels of BAP1." (PMID 29686263, 2018). "Rescue expression of BAP1, but not BAP1-C91A in two neuroblastoma cells lines reduced the proliferation rate at 48 and 72 h, compared with control cells." (PMID 29686263, 2018). "Independent of the neuroblastoma cell line tested, BAP1 expression promoted the downregulation of Bcl-2." (PMID 29686263, 2018).